PFDN6 (prefoldin subunit 6)
Description:
Binds specifically to cytosolic chaperonin (c-CPN) and transfers target proteins to it. Binds to nascent polypeptide chain and promotes folding in an environment in which there are many competing pathways for nonnative proteins.
Synonyms: HKE2; PFD6; KE-2; H2-KE2
Tractability: Small molecule: a structure with a bound ligand is known. PROTAC: UniProt records ubiquitination sites on it; ubiquitination databases record sites on it; its protein half-life has been measured.
Gene: Protein-coding gene on chromosome 6 (33,288,680 to 33,298,401, forward strand). Ensembl gene ENSG00000204220.
Subcellular location (Human Protein Atlas): Golgi apparatus; Nucleoplasm; Cytosol
Pathways (Reactome):
Metabolism of proteins: Prefoldin mediated transfer of substrate to CCT/TriC
Gene Ontology:
Molecular function: amyloid-beta binding; protein binding; protein-folding chaperone binding
Biological process: chaperone-mediated protein complex assembly; negative regulation of amyloid fibril formation; protein folding; protein stabilization
Cellular component: prefoldin complex; RPAP3/R2TP/prefoldin-like complex; protein folding chaperone complex
Genetic constraint (gnomAD): Loss-of-function variants: 5 observed, 18.17 expected, observed/expected ratio (o/e) 0.28, 90% interval 0.14 to 0.58. The upper end of that interval is the gene's LOEUF score, 0.58, which puts it in group 2 of 6, group 1 being the genes least tolerant of losing a copy. Missense variants: 101 observed, 147.12 expected, observed/expected ratio (o/e) 0.69, 90% interval 0.58 to 0.81. Synonymous variants: 51 observed, 61.68 expected, observed/expected ratio (o/e) 0.83, 90% interval 0.66 to 1.04.
Homologues: Orthologues: chimpanzee PFDN6 (100% identical), macaque PFDN6 (100% identical), rabbit PFDN6 (100% identical), dog PFDN6 (99% identical), mouse Pfdn6 (98% identical), guinea pig PFDN6 (98% identical), rat Pfdn6 (98% identical), zebrafish pfdn6 (72% identical), tropical clawed frog pfdn6 (64% identical), Drosophila melanogaster Pfdn6 (43% identical), Caenorhabditis elegans pfd-6 (43% identical).
Diseases named in the same sentence as PFDN6 in open-access papers:
PFDN6 is named in the same sentence as 14 diseases in open-access papers, as found by Europe PMC text mining. Sharing a sentence is not in itself a finding about the gene and the disease. The quoted sentences say what the papers report.
acute lymphoblastic leukemia (3 papers, 2020 to 2022). Leukemia with an acute onset, characterized by the presence of lymphoblasts in the bone marrow and the peripheral blood. "The low protein and mRNA expression of PFDN6 was reported to be associated with resistance to the chemotherapy drug dexamethasone in pediatric acute lymphoblastic leukemia." (PMID 35111762, 2021). "PFDN6 demonstrates potential diagnostic and prognostic values in childhood acute lymphoblastic leukemia (ALL) resistant to dexamethasone." (PMID 31957800, 2020). "In addition, PFDN6 serves as a potential biomarker of the prognosis of childhood acute lymphoblastic leukemia (ALL) and might predict the efficacy of chemotherapy." (PMID 36438659, 2022).
glioma (1 paper, 2024). A benign or malignant brain and spinal cord tumor that arises from glial cells (astrocytes, oligodendrocytes, ependymal cells). "PFDN6 was overexpressed in human glioma tissues and this significantly correlated with a poor survival rate." (PMID 38612711, 2024).
Tauopathies (1 paper, 2026). "Altogether, these data indicate that increased expression of Pfdn5 or Pfdn6 can remarkably counteract neuronal loss and delay the onset and progression of the neurodegenerative cascade induced in Tauopathy through a mechanism that involves Pfdn-mediated microtubule stabilization." (PMID 41533771, 2026). "However, coexpression of Pfdn5 or Pfdn6 with the pathological variant of hTau remarkably suppressed Tau-induced synaptic defects, prevented brain vacuolization, and rescued memory defects in multiple forms of tauopathies." (PMID 41533771, 2026).
infection (2 papers, 2020 to 2022). The state of being infected such as from the introduction of a foreign agent such as serum, vaccine, antigenic substance or organism. "E-30 infection leads to a down-regulation of proteins such as RADIXIN, PFDN6, DYNLB1, and BRK1." (PMID 33321840, 2020).
PFDN6 also shares sentences with these, for which no sentence is quoted: breast carcinoma (2 papers); lung carcinoma (1); malaria (1); memory impairment (1); neurodegenerative disease (1); ovarian carcinoma (1); parasitemia (1); prostate carcinoma (1); renal cell cancer (1); skin (1).